RAB2B (RAB2B, member RAS oncogene family)
Description:
The small GTPases Rab are key regulators of intracellular membrane trafficking, from the formation of transport vesicles to their fusion with membranes. Rabs cycle between active GTP-bound and inactive GDP-bound states. In their active state, drive transport of vesicular carriers from donor organelles to acceptor organelles to regulate the membrane traffic that maintains organelle identity and morphology. Regulates the compacted morphology of the Golgi (Probable). Promotes cytosolic DNA-induced innate immune responses. Regulates IFN responses against DNA viruses by regulating the CGAS-STING signaling axis (By similarity). Together with RAB2A redundantly required for efficient autophagic flux.
Synonyms: FLJ14824
Tractability: Small molecule: a structure with a bound ligand is known. Antibody: UniProt places it where antibodies can reach, with medium confidence; its Gene Ontology location is reachable by antibodies, with medium confidence. PROTAC: ubiquitination databases record sites on it; its protein half-life has been measured.
Gene: Protein-coding gene on chromosome 14 (21,459,020 to 21,476,960, reverse strand). Ensembl gene ENSG00000129472.
Subcellular location: Cell membrane; Endoplasmic reticulum membrane; Golgi apparatus membrane; Cytoplasmic vesicle, secretory vesicle, acrosome; Cytoplasmic vesicle, autophagosome membrane
Pathways (Reactome):
Metabolism of proteins: RAB geranylgeranylation
Gene Ontology:
Molecular function: G protein activity; protein binding; GTP binding; GTPase activity
Biological process: Golgi organization; positive regulation of exocytosis; defense response to virus; innate immune response; positive regulation of type I interferon production; vesicle-mediated transport; macroautophagy
Cellular component: extracellular exosome; Golgi apparatus; acrosomal vesicle; endoplasmic reticulum membrane; Golgi membrane; plasma membrane; autophagosome membrane; cytoplasm
Genetic constraint (gnomAD): Loss-of-function variants: 16 observed, 18.67 expected, observed/expected ratio (o/e) 0.86, 90% interval 0.58 to 1.3. The upper end of that interval is the gene's LOEUF score, 1.3, which puts it in group 5 of 6, group 1 being the genes least tolerant of losing a copy. Missense variants: 179 observed, 220.35 expected, observed/expected ratio (o/e) 0.81, 90% interval 0.72 to 0.92. Synonymous variants: 78 observed, 76.08 expected, observed/expected ratio (o/e) 1.03, 90% interval 0.85 to 1.24.
Homologues: Orthologues: dog RAB2B (98% identical), guinea pig RAB2B (97% identical), rabbit RAB2B (97% identical), rat Rab2b (95% identical), mouse Rab2b (95% identical), macaque RAB2B (94% identical), pig RAB2B (85% identical), tropical clawed frog rab2b (82% identical), chimpanzee RAB2B (78% identical), Caenorhabditis elegans rabr-4 (53% identical), Caenorhabditis elegans rabr-3 (53% identical). Paralogues in human: RAB2A (83% identical), RAB14 (57% identical), RAB4A (52% identical), RAB4B (51% identical), RAB11B (47% identical), RAB11A (46% identical), RAB39A (43% identical), RAB18 (42% identical), RAB1B (42% identical), RAB1A (42% identical), RAB37 (42% identical), RAB39B (41% identical), and 56 more.
Diseases named in the same sentence as RAB2B in open-access papers:
RAB2B is named in the same sentence as 15 diseases in open-access papers, as found by Europe PMC text mining. Sharing a sentence is not in itself a finding about the gene and the disease. The quoted sentences say what the papers report.
cervical cancer (3 papers, 2023 to 2024). A primary or metastatic malignant neoplasm involving the cervix. "And it has been reported that IGF2BP3 can promote cervical cancer cell proliferation by binding to the mRNA of RAB2B." (PMID 38355626, 2024). "RAB2B is overexpressed in cervical cancer and interacts with IGF2BP3 to promote cell growth and proliferation." (PMID 36712921, 2023). "It is known that Rab2b is related to the growth of cervical cancer cells." (PMID 36976668, 2023).
pancreatic cancer (2 papers, 2023 to 2024). "Further research on the specific role of RAB2B in pancreatic cancer is warranted to improve diagnostic accuracy and treatment strategies." (PMID 36712921, 2023). "Our results further demonstrate that RAB2B is closely associated with pancreatic cancer." (PMID 36712921, 2023). "Recent findings suggest that abnormal expression of mir-448 induces downregulation of RAB2B, significant reduction of pancreatic cancer cell proliferation, and promotion of cancer cell apoptosis." (PMID 36712921, 2023). "Furthermore, the diagnostic capability of combined AAT, RAB2B, IGFBP2, and CA19-9 for pancreatic cancer was significantly improved." (PMID 36712921, 2023). "In conclusion, AAT, RAB2B, and IGFBP2 were identified as potential biomarkers of pancreatic cancer through plasma proteomic iTRAQ analysis and further validated using ELISA and immunohistochemistry." (PMID 36712921, 2023). "Furthermore, collective application of AAT, RAB2B, IGFBP2, and CA19-9 in the diagnosis of pancreatic cancer was significantly more effective than each single index alone." (PMID 36712921, 2023). "AAT, RAB2B, and IGFBP2 could serve as effective biomarkers to facilitate the early diagnosis of pancreatic cancer." (PMID 36712921, 2023). "However, the expression patterns of RAB2B in blood and pathological tissues of pancreatic cancer patients have not been reported to date." (PMID 36712921, 2023).
brain tumors (1 paper, 2023). "Although it remains unclear whether Rab2 is related to promoting brain tumors, further research will clarify the precise role of Rab2b in tumor progression." (PMID 36976668, 2023).
Globozoospermia (1 paper, 2021). Any structural anomaly of the acrosome resulting in a round sperm head. "Further analysis of the function of FAM71F1 and its relationship with membrane trafficking-related proteins, such as RAB2A and RAB2B, will help to understand the mechanism that regulates acrosome formation and identify causative genes of globozoospermia." (PMID 34714330, 2021).
oral cancers (1 paper, 2020). "Finally, expression levels of a number of RAB family members segregate metastatic versus non-metastatic oral cancers, including RAB2B." (PMID 32872541, 2020).
pancreatic disease (1 paper, 2023). "Among these proteins, six (AAT, IGFBP2, RAB2B, PRDX2, RHOC, and LMNA) with functions closely related to pancreatic disease were selected for further validation." (PMID 36712921, 2023).
tumor (4 papers, 2018 to 2023). "In this context, we assessed the clinical value of 8 genes (RAB2B, RAB3B, RAB9A, RAB11B, RAB27A, RAB27B, STX1A, and VAMP7), which are implicated in sEVs biogenesis, as well as their association with overall and tumor-derived plasma sEVs levels." (PMID 36980570, 2023). "Our study shows that RAB27A, RAB27B, RAB2B, and RAB3B mRNA levels were lower in tumor tissues compared to tumor adjacent, non-malignant tissues (p < 0.001, p = 0.009, p = 0.011, and p < 0.001, respectively)." (PMID 36980570, 2023). "Interestingly, RAB27A, RAB27B, RAB2B, RAB3B mRNA levels were lower in tumor tissues compared to tumor adjacent, non-malignant tissues (p < 0.001, p = 0.009, p = 0.011 and p < 0.001, respectively)." (PMID 36980570, 2023).
infectious disease (1 paper, 2021). A disorder directly resulting from the presence and activity of a microbial, viral, or parasitic agent in humans. "Another species, C. burnetii, was mainly positively correlated with infectious disease-related genes like RAB2B, MICA, C1QTNF4, and YF6." (PMID 35250914, 2021).
RAB2B also shares sentences with these, for which no sentence is quoted: cancer (3 papers); autism spectrum disorder (1); colon adenocarcinoma (1); colon cancer (1); Hodgkins lymphoma (1); infection (1); melanoma (1).